EGFR (epidermal growth factor receptor)
Diseases named in the same sentence as EGFR in open-access papers (continued):
Sharing a sentence is not in itself a finding about the gene and the disease.
pancreatic cancer (continued). "A recent study indicates that NRF2 modulates mRNA translation, particularly, the translation of EGFR, to promote pancreatic cancer survival through a reduction in cellular ROS levels which maintains activation of translational regulatory proteins." (PMID 34247201, 2021). "Taken together, NETs facilitated EMT, migration and invasion via IL‐1β/EGFR/ERK pathway in pancreatic cancer cells." (PMID 33955688, 2021). "A previous research showed that the tumor marker CA 19-9 itself promotes the activation of EGFR (Epidermal Growth Factor Receptor) signaling in mice, suggesting an important role in the initiation and acceleration of pancreatic cancer." (PMID 33477505, 2021). "Subsequently, western blot assay was performed to detect EGFR expression of pancreatic cancer cells treated with 6-P." (PMID 34376189, 2021). "Epidermal growth factor receptor (EGFR), a transmembrane tyrosine kinase receptor, is frequently dysregulated in various tumors, including pancreatic cancer." (PMID 34552882, 2021). "In acinar cell plasticity and pancreatic cancer initiation, NFATc4 was found to be overexpressed and localized in the nucleus, thus activating the inflammation-induced epidermal growth factor receptor signaling pathway and upregulating the expression of Sox9." (PMID 33511023, 2021). "On the other hand, p38 MAPK was identified as a downstream target of EGFR in the regulation of cyclooxygenase-2 expression in pancreatic cancer cells." (PMID 34205482, 2021). "Molecular docking studies were carried out to understand the mechanism of action of some 2-alkoxycarbonylallyl esters against pancreatic cancer (MiaPaCa-2) cell line targeting the epidermal growth factor receptor (EGFR)." (PMID 33689046, 2021). "X-inactive specific transcript (XIST), a lncRNA, promotes pancreatic cancer proliferation by functioning as a ceRNA to relieve the inhibition of miR-133a on EGFR." (PMID 33419093, 2021). "Tat-interacting protein 30 (TIP30) downregulation by miR-10b-5p in pancreatic cancer cells was shown to lead to enhanced EGFR activity and downstream activation of extracellular signal-regulated kinases 1 and 2 (ERK1/2)." (PMID 34680585, 2021). "EGFR signaling leads to HIF1α activation as shown in pancreatic cancer where EGFR maintains glucose metabolism through the activation of ERK1/2 pathway." (PMID 34075041, 2021). "EGFR has been reported as a target of miR-146a in cancer, and miR-146a can block pancreatic cancer cell invasion and metastasis by inhibiting EGFR and IRAK1." (PMID 33985523, 2021). "Quercetin-7-O-glucoside has been reported to suppress pancreatic cancer by inhibiting the epidermal growth factor receptor (EGFR) signaling in the cell." (PMID 34685875, 2021). "Firstly, we found that both pancreatic precancerous lesions and invasive PDAC harbored high levels of EGFR compared with normal pancreas, and this phenomenon was confirmed by TCGA datasets of pancreatic cancer." (PMID 33422093, 2021). "First, we assessed the expression level of EGFR by IHC in 40 pancreatic cancer tissues and 20 paired normal pancreatic tissues." (PMID 33937024, 2021). "ANO9 was highly expressed in pancreatic cancer and promoted the metastasis of pancreatic cancer cells by increasing epidermal growth factor receptor expression." (PMID 34238763, 2021). "Overexpression of JAK-STAT pathway components, such as IL-6, EGFR, and Src, have also been seen in pancreatic cancer." (PMID 33546207, 2021). "As the EGFR/ERK/FOXA2/SOX9 axis regulates pancreatic cancer stem cells (PCSCs), inhibition of EGFR hampers the growth and motility of PCSCs mediated through this axis." (PMID 34591244, 2021). "In our previous study, we labeled the clinically available anti-EGFR antibody cetuximab with 64Cu and intraperitoneally (ip) administered it to an orthotopic xenograft mouse model of small resectable (<1 cm) pancreatic cancer." (PMID 35056963, 2021).
pancreatic cancer (continued). "In pancreatic cancer, several reports indicate that epidermal growth factor receptor (EGFR) signaling remains active and essential for tumor development despite downstream KRAS activation." (PMID 34070180, 2021). "In conclusion, all the findings above suggested that EGFR mediated HSF1 activation play a key role in pancreatic cancer initiation in vivo and in vitro." (PMID 33422093, 2021). "Increased expression of EGFR is commonly observed in malignancies such as lung, breast, and pancreatic cancers, making this receptor a major target for the development of anti-tumor therapies." (PMID 34178945, 2021). "In conclusion, the present study demonstrated that HSF1 plays a crucial role in the initiation of pancreatic cancer and that EGFR and its downstream signaling pathway sustain the pro-tumorigenesis effect of HSF1." (PMID 33422093, 2021). "PRMT5 also regulates FBW7 expression and EGFR/β-catenin signaling pathway to promote pancreatic cancer proliferation and tumorigenesis." (PMID 33495409, 2021). "We discovered that 6-P exerted anti-pancreatic cancer activity by decreasing the expression of EGFR and inhibiting the activity of AKT signaling." (PMID 34376189, 2021). "EGFR overexpression was an independent prognostic factor in pancreatic cancer patients receiving gemcitabine-based adjuvant chemotherapy." (PMID 34238922, 2021). "We therefore evaluated the combinatory effects of natural products with gemcitabine, as well as with the targeted agent gefitinib, an EGFR inhibitor, since EGFR inhibition has shown promising activity in pancreatic cancer, in the MIA PaCa-2 cell line." (PMID 34641401, 2021). "We had previously identified EGFR as well as EPHA2 being hyperphosphorylated in pancreatic cancer and esophageal cancer, respectively." (PMID 34298619, 2021). "Overexpression of ANO1 promotes pancreatic cancer cell migration via the ligand-dependent EGFR signaling pathway." (PMID 33901011, 2021). "Collectively, the AE@NPs prepared in this study possess great potential for pancreatic cancer treatment by dual suppressing of EGFR and STAT3 pathways and activating ROS-responsive p38 MAPK pathway." (PMID 33815107, 2021). "The increased pancreatic cancer cell proliferation by SPINK1 was further reported of which mechanism was through EGFR-mediated signaling activation." (PMID 33916984, 2021). "Epidermal growth-factor receptor (EGFR) overexpression is closely related to the progression of pancreatic cancer, while drug resistance of EGFR inhibitors (such as afatinib) limited its clinical application." (PMID 34629100, 2021). "To further investigate the underlying molecular mechanism of 6-P on EGFR, we firstly evaluated the mRNA expression levels of EGFR in pancreatic cancer cells treated with 6-P." (PMID 34376189, 2021). "This revealed a strong correlation between poor survival and high EGFR expression in human pancreatic cancer." (PMID 33937024, 2021). "Subsequently, gain- or lose-functional experiments were performed to evaluate the interaction between 6-P and EGFR on proliferation and metastasis of pancreatic cancer cells." (PMID 34376189, 2021). "EGF/EGFR signaling pathway has been known to promote the proliferation of pancreatic cancers via activating PI3K/AKT pathway." (PMID 34395235, 2021). "To this end, we tried to develop poly (lactic-co-glycolic acid) (PLGA) nanoparticles to co-load Alantolactone (ALA, a novel STAT3 inhibitor) and Erlotinib (ERL, an EGFR inhibitor) for pancreatic cancer to test our guess." (PMID 33815107, 2021). "It was found that emodin treatment at 30–90 μM markedly reversed afatinib (20 nM) resistance and promoted apoptosis via suppressing STAT3 and EGFR expression in pancreatic cancer cells (PANC-1 and BxPC-3)." (PMID 34629100, 2021). "This was explored in a phase I clinical trial whereby 19 patients with advanced pancreatic cancer were treated with dasatinib plus erlotinib (an EGFR inhibitor) (NCT01660971)." (PMID 33546207, 2021).
pancreatic cancer (continued). "Numerous studies have elucidated the role of EGFR in the early and late stages of pancreatic cancer progression." (PMID 34591244, 2021). "Genistein and erlotinib strengthened the effects of inhibiting EGFR/Akt/NF-κB signaling pathway on the occurrence and development of pancreas cancer." (PMID 33996561, 2021). "And, the inhibition of the formation of NETs and the blockade of IL‐1β can effectively attenuate the EGFR‐induced progression of pancreatic cancer." (PMID 33955688, 2021). "NET-associated IL-1β was recently found responsible for the EMT process of pancreatic cancer via EGFR-ERK pathway." (PMID 34868992, 2021). "There are now EGFR inhibitors on the market developed for use in other cancer types including lung and pancreatic cancer." (PMID 34165702, 2021). "It has been reported that EGFR affects the progression of pancreatic cancer through a variety of signalling pathways." (PMID 33955688, 2021). "Considering the differential expression of EGFR in pancreatic cancer and adjacent cancers, we were eager to find the epigenetic regulation mechanism of EGFR, especially the regulation effect of microRNAs on EGFR." (PMID 33937024, 2021). "Erlotinib, a small-molecule epidermal growth factor receptor (EGFR) tyrosine kinase inhibitor, demonstrated therapeutic efficacy against pancreatic cancer." (PMID 34552882, 2021). "An IPA interaction network analysis revealed the genes CCND1, CDK1A, CDK1B, Cyclin E (also known as CCNE1), and EGFR at the interface between the gemcitabine pathway and the pancreatic cancer signaling." (PMID 33925948, 2021). "Evidence from pancreatic cancer suggests that expression of oncogenic KRAS and loss of SMAD4 cooperate to induce the expression of EGFR and to promote invasion." (PMID 34298611, 2021). "In vivo and in vitro studies showed the greatest uptake and phototoxic effects for the nanocomplex conjugated with cetuximab, because most pancreatic cancer cells express EGFR on their surface." (PMID 34360829, 2021). "Although the EGFR inhibitor erlotinib has been given the green light from the FDA to treat pancreatic cancer for over 10-year period, detailed downstream signaling targets, e.g., KRAS, are promising and require further study." (PMID 34360896, 2021). "Accumulating evidence indicates that EGFR expression is significantly correlated with pancreatic cancer, high expression of EGFR frequently suggests a poor prognosis." (PMID 34376189, 2021). "It has been noticed that over-expression of EGFR is related to the severity of liver and pancreatic tumors and elevated death rate." (PMID 34535145, 2021). "Epidermal growth factor receptor (EGFR) is expressed in up to 60–90% of pancreatic cancers and is involved inducing cell growth and migration." (PMID 34195085, 2021). "Dual Src/EGFR inhibition has also been proposed as a treatment option for pancreatic cancer following a promising preclinical study." (PMID 33546207, 2021). "A previous study reported that the activation of the EGFR/AKT/β-catenin axis promoted EMT in pancreatic cancer cells." (PMID 33816467, 2021). "Literature results support the existence of a CD44–EGFR axis in colon, liver, lung, and pancreatic cancers, and the role of CD44s in EGFR signaling." (PMID 33981532, 2021). "Conversely, EFEMP1 enhanced pancreatic carcinoma cell growth by binding to EGFR to activate MAPK and Akt pathways." (PMID 34936728, 2021). "It has been shown that IMO administration can synergize with the anti-EGFR monoclonal antibody cetuximab by interfering with EGFR-dependent signaling both in vitro and in vivo systems of pancreatic carcinoma." (PMID 34884547, 2021). "In lung and pancreatic cancers, miR-146a is defined as an anti-tumor RNA, inhibits cell migration and invasion through suppression of EGFR signaling." (PMID 33248456, 2020).
pancreatic cancer (continued). "A recent study reported that CA19-9 expression in mice activated the epidermal growth factor receptor signaling, and it also cooperated with the Kras oncogene to develop aggressive pancreatic cancer." (PMID 31956368, 2020). "In summary, our study provides proof that PRMT5 promotes EMT in pancreatic cancer cells probably through activating EGFR/AKT/β‐catenin signalling." (PMID 31851779, 2020). "We also examined the functional interplay between PODXL and EGFR in pancreatic cancer cells in vitro." (PMID 32587323, 2020). "This study thus aimed to investigate the relationship between the expression of PODXL and EGFR in periampullary adenocarcinomas, including pancreatic cancer, with focus on morphological subtypes." (PMID 32587323, 2020). "EGFR is also overexpressed in several of cancer types, including lung, colon, head and neck, brain and pancreatic cancers, and is responsible for their development and progression." (PMID 31937753, 2020). "More recently, in another study overexpression of ITGA3 has been associated with a poor prognosis in patients with pancreatic cancer and ablation of ITGA3 was reported to be accompanied by a significant decrease in the EGFR expression and tumour growth." (PMID 31953437, 2020). "In vivo preclinical studies using pan-EGFR inhibitors such as canertinib have modulated EGFR downstream signaling and produced decreases in murine orthotopic pancreatic tumors via MUC4 inhibition." (PMID 33050151, 2020). "HER3 is often overexpressed in pancreatic cancer and is critical for mediating tumorigenesis via transactivation by epidermal growth factor receptor (EGFR)." (PMID 32545760, 2020). "Based on these results, we further investigated the requirement of EGFR in Ibr-7-induced radiosensitivity in pancreatic cancer." (PMID 32963499, 2020). "One example of this phenomenon is provided by the SW1990 pancreatic cancer cell line where oncogenic EGFR signaling is dampened by 1,3,4-O-Bu3ManNAc-driven sialylation." (PMID 32117864, 2020). "In our study, EGFR demonstrated increased phosphorylation activity in pancreatic cancer compared to control." (PMID 33213062, 2020). "The effect of TGF-β-induced expression and siRNA-mediated knockdown of PODXL and EGFR, were investigated in pancreatic cancer cells (PANC-1) in vitro." (PMID 32587323, 2020). "More importantly, we confirm that PRMT5 promotes EMT through EGFR/AKT/β‐catenin pathway in pancreatic cancer cells." (PMID 31851779, 2020). "Both KRAS and EGFR are essential mediators of pancreatic cancer development and interact with Argonaute 2 (AGO2) to perturb its function." (PMID 32499547, 2020). "The EGFR pathway contributes to pancreatic cancer growth and accelerates invasion of the cancer as a result of lnc00976 overexpression, which can deteriorate the outcome of patients." (PMID 33302876, 2020). "Our previous study showed that calreticulin (CRT) promoted EGF-induced epithelial-mesenchymal transition (EMT) in pancreatic cancer (PC) via Integrin/EGFR-ERK/MAPK signaling." (PMID 33028359, 2020). "Above all, we for the first time established the link between PRMT5 and EGFR/AKT/β‐catenin signalling in pancreatic cancer." (PMID 31851779, 2020). "In our study, Ibr-7 inhibited the expression of EGFR in pancreatic cancer cell lines, as we expected." (PMID 32963499, 2020). "It has also been reported that, G3 can inhibit EGF-mediated ERK phosphorylation and cyclin D1 expression, thus, inhibiting EGFR signaling pathways in pancreatic cancer models." (PMID 33167508, 2020). "There is an urgent need to unravel the intricate ERBB network in pancreatic cancer to better understand not only the role of EGFR, but also to show the potential significance of its relatives in order to establish more efficiently targeted therapies." (PMID 32335999, 2020). "In pancreatic cancer, epidermal growth factor receptor (EGFR) induced Src activation, followed by the phosphorylation of p130Cas/BCAR1." (PMID 32906721, 2020).
pancreatic cancer (continued). "Erlotinib (OSI-774) is an FDA-approved small-molecule EGFR tyrosine kinase inhibitor for use in pancreatic cancer." (PMID 33213062, 2020). "Inhibition of EGFR in combination with chemo/radiation therapy has been extensively tested in pancreatic cancer patients." (PMID 32974013, 2020). "In pancreatic carcinoma EGFR overexpression is measured in ~30% of cases and cytoplasmic overexpression of EGFR is considered a marker of poor prognosis in the ductal adenocarcinoma subtype." (PMID 33228060, 2020). "The expression frequency of EGFR in human pancreatic carcinomas is reported as 43% and 68.4% in primary invasive ductal carcinoma of the pancreas with elevated expression of EGFR activating ligands also reported." (PMID 33213062, 2020). "Small studies have evidenced that pancreatic carcinoma cells produce a higher amount of sEVs than their normal counterparts, and that the sEVs display EGFR protein." (PMID 33228060, 2020). "In fact, several studies had showed that combined targeting of EGFR and ErbB2 did result in enhanced efficacy in treatment of pancreatic cancer." (PMID 30961642, 2019). "VPA-induced apoptosis in the EGFR/ErbB2/ErbB3-coexpressing pancreatic cancer cells was also confirmed by flow cytometry analysis." (PMID 30961642, 2019). "It has also been reported that integrin β5 forms a complex with epidermal growth factor receptor (EGFR) and contributes to pancreatic cancer metastasis." (PMID 31052260, 2019). "After conjugation with a-EGFR (a monoclonal antibody derivative), Ag NPLs were readily taken up by EGFR-overexpressing pancreatic cancer cells by receptor-mediated endocytosis and exhibited little or no toxicity." (PMID 31315232, 2019). "Collectively, our results demonstrate that VPA selectively exerts anti-tumor activity in vitro through induction of growth inhibition as well as apoptosis in the EGFR/ErbB2/ErbB3-coexpressing pancreatic cancer cells." (PMID 30961642, 2019). "EGFR inhibitors are less effective when the driver mutations are not specific to EGFR and instead harbored in KRAS, which is particularly important in pancreatic cancer because KRAS is mutated in approximately 95% of PDAC." (PMID 30921351, 2019). "We demonstrates that much lower drug concentrations can be used to obtain the actual EGFR inhibition in pancreatic cancer." (PMID 30921351, 2019). "We also demonstrated the EGFR expression levels of eight human pancreatic cancer cells and H6c7 cells." (PMID 30808960, 2019). "The only targeted therapy approved for pancreatic cancers is the epidermal growth factor receptor (EGFR) inhibitor Erlotinib, which is administered in combination with Gemcitabine and results in a modest increase in overall survival." (PMID 31527715, 2019). "SPINK1-treated pancreatic cancer cells showed increased phosphorylation of EGFR as well as activation of MAPK and STAT3; this response was attenuated in cells treated with the EGFR inhibitor AG1478." (PMID 30778387, 2019). "In our attempt to determine the underlying mechanisms of anti-pancreatic cancer activity of VPA, the possible effect of VPA on expression of EGFR, ErbB2 and ErbB3 was investigated." (PMID 30961642, 2019). "Kaempferol inhibits pancreatic cancer cell growth and migration through the blockade of an EGFR‐related pathway." (PMID 31139404, 2019). "EGFR over-expression has been confirmed to confer a poor survival, correlating with a more advanced stage and the presence of metastasis in pancreatic cancer." (PMID 30760292, 2019). "EGFR is aberrantly activated in a number of epithelial tumors and its overexpression has been detected in up to 90% of pancreatic tumors." (PMID 30809507, 2019). "Taken together, the results indicate that rhein offers a novel blueprint for pancreatic cancer therapy, particularly when combined with EGFR inhibitors." (PMID 30674340, 2019).